RN7SKP71 (RN7SK pseudogene 71)
Gene: Miscellaneous RNA gene on chromosome 12 (112,267,077 to 112,267,394, forward strand). Ensembl gene ENSG00000201428.
Homologues: Orthologues: chimpanzee 7SK (94% identical), mouse Gm54754 (78% identical). Paralogues in human: RN7SKP79 (81% identical), 7SK (79% identical), RN7SKP203 (78% identical), RN7SKP255 (78% identical), RN7SKP176 (77% identical), RN7SKP124 (77% identical), RN7SKP90 (77% identical), RN7SKP171 (76% identical), RN7SKP294 (76% identical), RN7SKP133 (75% identical), RN7SKP180 (75% identical), RN7SKP204 (75% identical), and 284 more.